C17orf114 (chromosome 17 open reading frame 114)
Gene: Protein-coding gene on chromosome 17 (4,801,159 to 4,807,013, reverse strand). Ensembl gene ENSG00000262165.
Homologues: Orthologues: chimpanzee C17orf114 (97% identical), macaque C17orf114 (97% identical), pig C17orf114 (91% identical), dog C17orf114 (82% identical), mouse Gm40193 (82% identical), rabbit C17orf114 (81% identical), rat Tomm7-ps4 (77% identical), guinea pig C17orf114 (75% identical).